CCL2 (C-C motif chemokine ligand 2)
Diseases named in the same sentence as CCL2 in open-access papers (continued):
Sharing a sentence is not in itself a finding about the gene and the disease.
tumor (continued). "Rapid recruitment of circulating inflammatory monocytes to the site of tumor growth can be achieved by specific signaling molecules such as CCL2, CSF-1, mediators, and complement components (in particular C5)." (PMID 37138860, 2023). "Because CCL2 production in tumors facilitates the accumulation of immune-suppressive, tumor-promoting TAMs, it has become a molecular target for cancer treatment." (PMID 37865750, 2023). "For example, CCL2 was highly expressed in aged tumor cells to recruit monocyte from peripheral blood." (PMID 36761752, 2023). "Plasma concentration of CCL2 increased markedly in all mice as tumor burden increased and was significantly greater in mice treated with anti-CCL2 antibody compared to untreated mice." (PMID 37964011, 2023). "Specifically, treatment with a higher dose of smTRAIL allowed tumor cells to recruit TAMs (mainly C1q+ macrophages) by secreting CCL2." (PMID 37605148, 2023). "Accordingly, TGF-β1, IL-10 and CCL2 protein levels were significantly increased, and TNFα, IL-6, IL-1β and IL-12p40 protein levels were significantly decreased in tumor tissues in mice with MO-Mettl3 macrophages compared with mice with MO–nc macrophages." (PMID 37402945, 2023). "The CCL2 increase by co-cultivation seems parallel to the increase in tumor cell proliferation, suggesting a possible autocrine tumor cell activation." (PMID 36835050, 2023). "Tumor growth inhibition is observed with the use of Anti-CCL2 antibodies alone or in combination with chemotherapeutic drugs." (PMID 36739406, 2023). "The average tumour latency of the PyMT controls and PyMT/CCL2 mice was 8 and 7.5 weeks, respectively." (PMID 37108548, 2023). "It was also suggested that the administration of anti-CCL2 Ab during the tumor induction phase is detrimental, whereas Ab treatment is inhibitory after the tumor induction phase or when tumors are already established." (PMID 37208442, 2023). "Blocking ATX activity changed the phenotype of the mice by decreasing the plasma concentrations of CXCL9, CXCL10, and CCl2 and the tumor concentrations of LIF, TGFβ1, TGFβ2, and prolactin." (PMID 37296899, 2023). "The Ccl2–Ccr2 signaling axis is known to have a key role in tumor and metastasis progression and was tested as a therapeutic target in clinical trials." (PMID 37756565, 2023). "Next, we examined the expression of three ER stress-related cytokines identified from ContactTracing, Ccl2, Cxcl1 and Il11, in 4T1 cells and validated their dependence on tumour-intrinsic STING activation." (PMID 37612508, 2023). "In support of these data, RNA seq data of cultured NT193 tumor cells confirmed that CCL2 expression was higher in cells expressing high TNC compared to TNC− cells." (PMID 37176074, 2023). "CCL2 had an equal effect on the recruitment of CD206+ (pro-tumor) and MHC II+ (antitumor) populations of macrophages, thus balancing the pro- and antitumor macrophage cell populations." (PMID 37208442, 2023). "As CCL2 functions as the most critical chemokine in the recruitment of Mφ to tumor sites, we analyzed transcriptome data from IL‐1β‐treated A549/ U87MG cells and found that CCL2 was one of the most highly upregulated chemokine genes." (PMID 37009412, 2023). "In pre-clinical models, CCL2 blockade in combination with radiation delayed tumor growth and decreased tumor proliferation and vascularity." (PMID 37209684, 2023). "It is confirmed that the nanoparticle-contained cells, known as DiDBV2-Fe, show a strong tumor chemotaxis to monocyte chemoattractant protein-1 (CCL2) excreted by U87MG tumor cells." (PMID 37596631, 2023).
tumor (continued). "Strikingly, CCL2/MCP-1, well known to mediate the recruitment of monocytes in the hypoxic areas, were more concentrated in 3- and 4-culture tumor spheroids, supporting our results on the spatial localization of monocytes in the hypoxic area of the spheroid." (PMID 37519820, 2023). "Administrating the antagonist of CCL2 has a reduction effect on tumor growth, decreasing macrophage infiltration and inhibiting angiogenesis." (PMID 38017494, 2023). "Chemokines have been described as being crucial in immune and inflammatory reactions, tumor-derived CCL2 expression positively correlates with TAM." (PMID 37221577, 2023). "The cytokine/chemokine array revealed that CCL2 is the most highly expressed chemokine in the plasma of GEM-treated tumor-free mice." (PMID 36976637, 2023). "Palpable primary tumours collected from PyMT control mice at 9 weeks of age had an average of 497.54 ± 85.02 macrophages per mm2, and PyMT/CCL2 mice had an average of 683.00 ± 97.81 macrophages per mm2." (PMID 37108548, 2023). "Knockdown of CCL2 in neoplastic MCs resulted in reduced tumor growth in vivo compared with CCL2-expressing cells and reduced microvessel density in the tumors." (PMID 37025992, 2023). "A previous study has demonstrated that CCL2 produced by tumor and stromal cells in the TME can promote the recruitment of monocytes to the TME and the polarization of TAMs towards the pro-tumoral M2 type." (PMID 36674955, 2023). "Antitumor functions of NF-κB are attributed to its signaling that recruits the T-cells in the tumor cell vicinity, leading to tumor regression apart from cytokine and chemokine activation harbouring the C-C and chemokine (C-C motif) ligand 2 (CCL2) motifs." (PMID 37970206, 2023). "Our research shows a high expression of CCL2 in tumor cells and MDMs, and the expression is much higher in aged group." (PMID 36761752, 2023). "Meanwhile, IL‐1β induced CCL2 secretion from tumor cells and exhibited a strong ability to recruit Mφ into the tumor site." (PMID 37009412, 2023). "CCL-2 acts as a key factor in the recruitment of TAMs, contributing to increased peripheral monocytes and increased monocyte recruitment in tumor TME." (PMID 37810971, 2023). "Trabectedin exerts its activity on both tumor cells and the tumor microenvironment by reducing the production of inflammatory mediators (e.g., CCL2 or CXCL8)." (PMID 36857355, 2023). "As a consequence of PTEN loss, there is increased secretion of C-C motif chemokine ligand 2 (CCL2), which in turn induces recruitment of IBA1+ myeloid cells, enhances brain metastatic tumor cell proliferation, and reduces apoptosis." (PMID 36765679, 2023). "The PGF2 tumor phenotype has elevated CCL2, IL6, IL1A, and IL1B, all of which are secreted by uterine smooth muscle cells treated with PGF2." (PMID 36834607, 2023). "Similar to previous studies, our study found that increased IL-6 secretion by tumor exosomal cSERPINE2-educated TAMs elevated the expression of CCL2 to enhance TAMs infiltration." (PMID 36797769, 2023). "Surprisingly, compared with mice injected with parental TRAMP-C2 cells only, co-injection with either WT or CCL2 KO MSCs significantly reduced the tumor growth rates; however, the CCL2 KO (#1) exhibited enhanced inhibitory effects." (PMID 36672395, 2023). "Although inflammation is one of the hallmarks of cancer, the role of CCL2-mediated inflammation in tumour development and progression is more complex." (PMID 37108548, 2023). "For instance, elevated levels of tumor-derived chemotactic protein CCL2 have been correlated with high numbers of TAMs and poor patient prognosis in various cancer types." (PMID 36670988, 2023). "Tumor-derived granulocyte-colony stimulating factor (G-CSF), IL-6, VEGF, and CCL2 cause MDSCs migration to HCC-TME." (PMID 37007125, 2023).
tumor (continued). "SASP factors IL-6, IL-8, and CCL2 induce the recruitment of various antitumor immune cells, such as natural killer (NK) cells, M1 macrophages, and T helper 1 cells, which can exert a tumor clearance function." (PMID 38275386, 2023). "The antibody did not affect murine CCL2 levels but significantly increased human CCL2 levels in the plasma or tumor interstitial fluid." (PMID 37208442, 2023). "First, our observation of monocyte infiltration and elevated CCL2 expression in the irradiated tumor is consistent with pre-clinical models that exhibit CCL2-mediated recruitment of monocytes following radiation." (PMID 37209684, 2023). "CCR2, the CCL2 receptor, represents another way of targeting CCL2 release, that in combination with anti-PD-1 therapy resulted in sensitization and increased tumor response compared to monotherapy." (PMID 38313431, 2023). "In comparison to the commercially available CCL2 antibody, this approach demonstrated improved therapeutic effectiveness and notable inhibition of tumor growth." (PMID 37654704, 2023). "Cancer-associated immune cells are recruited in the tumor niche in response to several chemokines and cytokines released from tumor cells, such as CCL2, IL-8, CXCL12, and CCL5." (PMID 37592292, 2023). "On the contrary, when the MSCs were co-injected with tumor cells in the immune competent syngeneic mice, the CCL2 KO MSCs indeed showed increased anti-tumor effects compared to wildtype MSCs." (PMID 36672395, 2023). "This infiltration of irradiated tumors by monocytes has been reported in pre-clinical models and is mediated by CCL213,18; notably, we also find higher levels CCL2 mRNA in the irradiated tumor." (PMID 37209684, 2023). "Studies have shown that NF-κB can recruit TAMs to the tumor microenvironment through chemokine (C-C motif) ligand 2 (CCL2), and regulate the M2-type polarization of TAMs, promoting tumor progression." (PMID 37291549, 2023). "They found that the splenic stromal cells of tumor-bearing mice recruited specific subsets of HSPCs into peripheral circulation via the CCL2/CCR2 axis." (PMID 37415162, 2023). "M1‐TAMs are associated with inflammatory factors, including CCL2/3/4, CXCL3, and TNF, which recruit T cells, immature DCs, and NK cells in the tumor microenvironment." (PMID 36529697, 2023). "LMP1 can promote the expression of CCL5 and CCL2 in NPC cells, both of which can recruit tumour‐associated macrophages." (PMID 36519208, 2023). "We report that tumor cell–derived adrenomedullin has a pro-angiogenic as well as a direct tumor-promoting effect, and that endothelium-derived CC chemokine ligand 2 (CCL2) suppresses adrenomedullin-induced tumor cell proliferation." (PMID 36374225, 2023). "CCL2 knockdown in cancer cells led to a marked reduction in macrophage infiltration, tumor cell proliferation, skin erythema, and metastasis." (PMID 37208442, 2023). "Chemokines produced by tumor cells, immune cells, and tumor stromal cells, including CC­chemokine ligand 2 (CCL2), CCL5, CXC­chemokine ligand 12 (CXCL12, also known as SDF1) and CXCL1, are involved in this process." (PMID 36824409, 2023). "RT-PCR results showed that mRNA expression of CCL2 emerged as the most prominently chemokine in circ_0009092 transfected tumor cells." (PMID 38008713, 2023). "In cluster 4, which mostly existed in the gem group, cells expressed high levels of CCR2, CCL2, and S100A4 genes that are associated with tumor progression and metastasis." (PMID 37324492, 2023). "More importantly, IL-6 in turn increased the EIF4A3 and CCL2 levels within tumor cells in a positive feedback mechanism, further enhancing tumor cSERPINE2 biogenesis and promoting the recruitment of TAMs." (PMID 36797769, 2023). "Supplementation of the medium with CCL2 alone was insufficient to replicate the conditioned medium’s effect on the tumor cell line." (PMID 37572121, 2023).
tumor (continued). "The AKT pathway plays an important part in tumor growth, and recent studies have even revealed that the AKT pathway regulates the expression of CCL2 and affects the tumor immune microenvironment." (PMID 36831602, 2023). "Various data show that enhanced levels of CCL2 in different tumors promote tumor progression and metastasis." (PMID 36374225, 2023). "Our data show a new role of CCL2 as an angiocrine factor of the tumor microenvironment which suppresses tumor progression by directly acting through CCR2 expressed by tumor cells." (PMID 36374225, 2023). "The expression of the pro-inflammatory chemokines CCL5 and CCL2 increased in HIF–1-deficient tumors, which in turn increased the infiltration of cytotoxic lymphocytes into the tumor." (PMID 37056346, 2023). "In this study, we investigated MC/OSCC interactions, considering the influence on tumor cell proliferation and invasion and identified CC chemokine ligand 2 (CCL2) as a potential interaction mediator." (PMID 36835050, 2023). "The absolute amount of CCL2 secreted into the supernatant during GM-CSF stimulation over 7 days was relatively low compared to the amount of CCL2 that tumor cells secrete, indicating that additional autocrine stimulation seems unlikely." (PMID 37176074, 2023). "After we collected the tumors and measured their weights, only the tumor co-injected with CCL2 KO MSCs showed a reduction with statistical significance (T vs. T+#1)." (PMID 36672395, 2023). "Splenomegaly was also reduced in Ccl2-/- mice and Ccr2-/- mice, likely reflecting the smaller tumor size in those mice." (PMID 37208442, 2023). "Flow cytometry analysis revealed that tumor-specific CCL2 overexpression in the context of T/P-induced senescence was sufficient to significantly increase NK cell accumulation into PDAC without affecting NK cell activation." (PMID 37142692, 2023). "Major initiators of tumor inflammation such as CCL2, CXCL1, CXCL2, CXCL11, CSF1, LTB, and TNFSF10 were found to increase in both cell lines, while inflammation suppressors like IL13and IL1RN were decreased." (PMID 36831395, 2023). "Although CCL2 was once considered to stimulate host anti-tumor responses in a T-lymphocyte-independent manner, it was recently widely recognized for its significant pro-tumor effects." (PMID 38204755, 2023). "Hepatocellular carcinoma cells that underwent EMT secreted CCL2 to recruit TAMs that facilitated tumor metastasis." (PMID 36841801, 2023). "Our findings show tumor-promoting roles of adrenomedullin and identify CCL2 as an angiocrine factor controlling adrenomedullin formation by tumor cells." (PMID 36374225, 2023). "C. albicans infection caused the upregulation of CCL2 concentration as well as CD163, PD-L1, and GAL-9 expression on tumor-associated macrophages (TAMs) in oral tumors isolated from C3H/HeN-SCC VII mice." (PMID 37067414, 2023). "TAM are derived from circulating monocytes that are recruited to the tumor site by various chemokines and cytokines, such as CCL2, CSF-1, and VEGF." (PMID 38130725, 2023). "The results confirmed that BCL2A1 was positively correlated with this series of tumor-related macrophage markers, especially CCL2 and CD68." (PMID 37889551, 2023). "CCL2 plays a vital role in the generation of TAMs and is related to the growth of TNBC tumors; inhibiting CCL2 can block tumor stem cell renewal and M2 recruitment, thereby inhibiting the progression of TNBC." (PMID 38213533, 2023). "Under CCL2 knockout conditions, the tumor-promoting effect of MEX3A was found to be significantly attenuated." (PMID 37153567, 2023). "Low passage tumor alone secreted high concentrations of CCL2/MCP1, CXCL8/IL-8, CXCL1/GRO, IL-6, CXCL10/IP10, G-CSF, TGFβ1, MMP1, CCL3/MIPα, GM-CSF and EGF." (PMID 37063842, 2023). "In the TME, the role of CCL2 is particularly obvious; it can attract M2 macrophages to accumulate in tumor tissues." (PMID 37926835, 2023).
tumor (continued). "For instance, overexpression of tumor suppressor miR-124 in CAFs promotes its uptake by neighboring cancer cells, where miR-124 directly targets chemokine (C-C motif) ligand 2 (CCL2) and interleukin 8 (IL-8)." (PMID 37345170, 2023). "Tumor cells recruit monocytes expressing its receptor CCR2 by releasing chemokines such as CCL2 and activating them into M2-like TAM." (PMID 37138860, 2023). "Tumor SEVs mediate the migration of MDSCs and contribute to the metastasis of murine BC cells (4T1 cells) to the lung in a CCL2-dependent manner." (PMID 37108371, 2023). "The basal tumor cells of cSCC samples in our study highly expressed CCL2, CXCL14, FTH1, MT2A, which is consistent with the findings in Tumor_KC_Basal." (PMID 38099574, 2023). "The average total tumour burden at 9 weeks of age was 268.67 ± 19.04 mg for PyMT controls and 211.93 ± 45.43 mg for PyMT/CCL2 mice." (PMID 37108548, 2023). "Tumor cells directly or indirectly recruit inflammatory monocytes by releasing chemokines (cc-chemokine ligand 2 (CCL2)) or inducing local endothelial activation (E-selectin expression)." (PMID 37046617, 2023). "In vitro, conditioned media from KPC1 cells overexpressing CCL2 and pre-treated with T/P produced significantly more NK cell migration through a transwell insert, demonstrating that CCL2 secretion by senescent tumor cells can facilitate NK cell chemotaxis." (PMID 37142692, 2023). "A bioinformatic analysis points to a requirement for high levels of both TNC and CCL2 with enriched binding to both glycan moieties, as well as with tumor-infiltrating B cells and/or antibody-mediated immune responses." (PMID 37176074, 2023). "Previous studies have shown that the CCL2/CCR2 axis is a critical chemokine signaling pathway that creates the tumor microenvironment through the recruitment of immunosuppressive cells." (PMID 36810973, 2023). "Molecular signals from tumor and stromal cells, notably the chemokine CCL2, actively attract circulating monocytes to the tumor vicinity." (PMID 38035068, 2023). "It is known that CCL2 secreted by tumor and stromal cells can recruit immune cells, including macrophages and peripheral leukocytes, to shape the tumor immune microenvironment (TIME), a key factor determining the efficacy of ICB therapy." (PMID 38057698, 2023). "When TAM recruitment is reduced by decreasing CCL2 expression in the tumor niche, there is an increase in CXCR2 ligand expression, which leads to increased neutrophils recruitment." (PMID 37408240, 2023). "In contrast, serum CCL2 levels were undetectable in tumor-bearing Ccl2-/- mice, and the level of Ccl2 mRNA in tumors of Ccl2-/- mice was markedly lower." (PMID 37208442, 2023). "MSC-derived CCL2 is involved in the tumor-promoting functions of macrophages, and targeting CCL2 has been a therapeutic approach." (PMID 36672395, 2023). "One proposed mechanism for trabectedin’s anticancer action is lowering CCL2 levels, reducing the number of macrophages in tumor tissues." (PMID 37211559, 2023). "CAFs play a tumor-promoting role in esophageal carcinoma through IL-6- and CCL2-promoted tumor migration and TAM-like polarization and invasion of macrophages." (PMID 37046676, 2023). "In this study, tumor cells stimulated by M2 exosomes secreted more CCL2 and induced macrophage infiltration and M2 polarization." (PMID 37904170, 2023). "Following genetic KRAS silencing, HDAC5 upregulation causes remodelling of the TME via SOCS3-dependent upregulation of CCL2 and CCL7, and recruitment of immunosuppressive tumour-associated macrophages (TAMs)." (PMID 36864508, 2023). "Therapies that block the CSF-1/CSF-1R axis and that, in general, chemokine-targeted therapies (antiCXCL12 or anti-CCL2) not only have the effect of acting directly on tumor growth and propagation but also target the TME formed by immune cells." (PMID 37958702, 2023).